GCG (glucagon)
Diseases named in the same sentence as GCG in open-access papers (continued):
Sharing a sentence is not in itself a finding about the gene and the disease.
cancer (continued). "Moreover, its antiangiogenic potential requires careful evaluation for use in patients with cancer as systemic delivery of glucagon may disturb the balance of blood glucose levels and increase the risk of developing metabolic disorders." (PMID 38072640, 2024). "However, the pathophysiological role of glucagon in cancer is not well known." (PMID 29535833, 2018). "Given the diverse effects of GLP1R and GCG expression on cancer survival, clinicians should exercise caution when prescribing GLP-1 receptor agonists, particularly in patients with known cancer risks." (PMID 39777709, 2025). "Our findings contribute to filling this gap, demonstrating that glucagon’s interactions with both the GCGR and GLP-1R add complexity to its role in cancer biology, potentially driving adaptive mechanisms in pNET cells." (PMID 40649254, 2025). "The heterogeneity of the cancers analyzed and the differing effects of GLP1R and GCG expression indicate that the relationship between GLP-1 signaling and cancer is likely more intricate than this study alone can elucidate." (PMID 39777709, 2025). "It was also enriched in the glucagon signaling pathway, Glycolysis/Gluconeogenesis, Carbon metabolism, AMPK signaling cascade and Central carbon metabolism in cancer, and other biological pathways (KEGG)." (PMID 40998906, 2025). "In contrast, the GAA2 group exhibited predominant alterations in glycerophospholipid metabolism, choline metabolism in cancer, citrate cycle (TCA cycle), sphingolipid metabolism, cAMP signaling pathway, glucagon signaling pathway, and tyrosine metabolism." (PMID 41300388, 2025). "As for methylation, GNGT1, KCNS3, GCG and PPKACG tended to be hypomethylated in pan-cancer while ADCY8 tended to be hypermethylated." (PMID 39104385, 2024). "Conversely, DEMs in the BFC_vs_BMC comparison were predominantly involved in pathways such as the glucagon signaling pathway, citrate cycle (TCA cycle), central carbon metabolism in cancer, and pyruvate metabolism." (PMID 39201815, 2024). "Regarding HRAS mutant cancer cells, the downregulated pathways via Kegg enrichment analysis included Wnt signaling, hypoxia-inducible factor 1 (HIF-1) signaling, glucagon signaling, Prolactin signaling, and Hippo signaling, among others." (PMID 38982514, 2024). "Regarding HRAS mutant cancer cells, the downregulated pathways included Wnt signaling, HIF-1 signaling, glucagon signaling, Prolactin signaling, and Hippo signaling." (PMID 38982514, 2024). "The results showed that the DEGs were mainly enriched in the transcriptional misregulation in cancer, FoxO signaling pathway, AMPK signaling pathway, glucagon signaling pathway, and regulation of glucose metabolism." (PMID 36050999, 2022). "For example, FOXA1 and FOXA2, both of which play an important role in α-cell glucagon biosynthesis and secretion, are O-GlcNAc modified by OGT in cancer cells, and this modification is important for the stability of the protein." (PMID 33460647, 2021). "Pathway enrichment revealed enrichments in the following cancer-related pathways in the order of significance: FoxO signaling, proteoglycans, glucagon, thyroid hormone, AMPK, viral, and general cancer pathways." (PMID 34804955, 2021). "In Hp+-AG-IM network the expression of APOA4, GCG, CYP3A4, XPNPEP2 and FOXP3, JUN were statistically different in the comparison of normal and cancer in TCGA database." (PMID 32547867, 2020). "It is worth noting that the expression of APOA4, GCG, CYP3A4, XPNPEP2, and FOXP3, JUN were different between cancer and normal samples in TCGA database." (PMID 32547867, 2020). "Glucagon acts through binding to its receptor, glucagon receptor (GCGR), and cross-talk between GCGR-mediated signals and signaling pathways that regulate cancer cell fate has been unveiled." (PMID 29535833, 2018).
cancer (continued). "This study was designed to evaluate the prognostic significance of GLP1R expression across various cancer types, with the hypothesis that GLP1R expression might serve as an indicator of certain cancers’ sensitivity to glucagon/GLP-1 signaling." (PMID 39777709, 2025). "KEGG enrichment analysis demonstrated significant associations between the identified GRDEGs and several critical metabolic pathways, notably the glucagon signaling pathway, Glycolysis/Gluconeogenesis, Carbon metabolism, AMPK signaling circuit, and Central carbon metabolism in cancer." (PMID 40998906, 2025). "The significant differential metabolic pathways between the CK0 group and the T0 group were glyoxylate and dicarboxylate metabolism, a glucagon signaling pathway, citrate cycle (TCA cycle), carbon metabolism, central carbon metabolism in cancer, purine metabolism, amino acid metabolism, etc.." (PMID 40646988, 2025). "Up until now, studies have predominantly focused on cancers derived from pancreatic ductal epithelium cells, and there have been no reports on EEF1A2 in cancers originating from glucagon-producing pancreatic islet cells." (PMID 38172654, 2024). "In terms of metabolism, the glucagon signaling pathway down-activates glycogenolysis and glycolysis by GYS and PKM, respectively, which are circuits that exhibit differential behaviors depending on the cancer type." (PMID 37834179, 2023). "Since previous studies in cancer models demonstrated instances of mitochondrial CREB localization, we performed nuclear fractionations on SNU398 eGFP or GCGR cells treated with glucagon to verify if activated p-CREB S133 was spatially capable of facilitating gluconeogenic gene transcription." (PMID 35123542, 2022). "We conclude that glucagon signaling has the potential to oppose cancer growth but may not represent a clinically translatable option at this time." (PMID 35123542, 2022). "Thus, the binding of glucagon to the glucagon-like peptide-1 receptor (GLP-1R) may subvert the system and contribute to hyperglucagonemia and the activation of signalling that may favour cancer." (PMID 40649254, 2025). "Thus, glucagon treatment alone may not be as powerful as blocking tumor growth, but might produce a synergistic antitumor effect when combined with other cancer therapies, since patients usually receive several anticancer treatments." (PMID 38072640, 2024). "Additionally, in vitro studies showed the short-term effect of glucagon on cancer cells, which could not clearly elucidate the role of hyperglucagonemia on cancer cell progression." (PMID 29535833, 2018).
metabolic disease (118 papers, 2009 to 2026). A congenital disorder (due to inherited enzyme abnormality) or acquired (due to failure of a metabolically important organ) disorder resulting from an abnormal metabolic process. "We summarized the physiologic actions of GLP-1, GIP and GCG and their association with metabolic disorders." (PMID 41465555, 2025). "In recent years, scientists have found TRPV1 plays an important role in metabolic diseases and is associated with many signaling pathways such as pancreatic secretion, glucagon signaling, inflammatory mediator regulation of TRP channels, IR, and AMPK." (PMID 35694255, 2022). "Hyperglucagonemia is a common feature across several metabolic conditions, not only in adults but also in pediatric populations, suggesting that glucagon may represent both a pathogenic factor and a potential therapeutic target in metabolic disease." (PMID 41149695, 2025). "More recently, novel co-agonists of GLP-1, glucose-dependent insulinotropic polypeptide (GIP) and glucagon have also been approved or are under evaluation for the treatment of diabetes and associated metabolic diseases, holding potential for cardiovascular risk reduction." (PMID 37542009, 2023). "In particular, the multiple metabolic actions of glucagon highlight the importance of understanding the contributions of individual hormone action to inform the safe, effective and tailored use of GLP-1/glucagon co-agonists to target weight loss and metabolic disease in the future." (PMID 34566894, 2021). "In addition, the altered circadian rhythms and irregular diets associated with shift work and SWSD affect insulin and glucagon secretion, disturbing metabolic homeostasis and increasing the risk of cardiovascular disease and metabolic disorders, which are risk factors for premature ejaculation." (PMID 38961338, 2024). "Hyperglucagonemia, characterized by elevated plasma glucagon levels, is a well-known feature of various metabolic disorders, including NAFLD and CKD." (PMID 40822953, 2025). "Multi-receptor agonists combining GLP-1, GIP, and glucagon signaling represent a paradigm shift in metabolic disease treatment." (PMID 41153663, 2025). "The TCA cycle, glucagon pathway and purinergic signalling pathway are the key loops of metabolic disorders." (PMID 38355572, 2024). "Ultimately, however, our findings will continue to re-frame the proposed used of glucagon in so-called multi-agonist metabolic disease therapeutics." (PMID 39236784, 2024). "In general, more (longitudinal and modeling) studies in the pediatric population concerning glucagon and its role in metabolic disease are needed." (PMID 39027470, 2024). "In DM2-related metabolic disorders, there are differences in the metabolic mediators such as gastrointestinal incretins, C-peptide, glucagon, and PAI-1." (PMID 38397883, 2024). "Intriguingly, the dysregulation of many hormones, such as insulin, glucagon, and sex hormones, is often observed in metabolic diseases, and emerging evidence indicates them as critical regulators of ferroptosis." (PMID 39346540, 2024). "The review highlights the potential therapeutic applications of targeting the glucagon pathway in the treatment of metabolic disorders." (PMID 37764697, 2023). "Overall, investigating the intricate mechanisms governing glucagon’s diverse functions is vital to unraveling its role in metabolic disorders like T2DM." (PMID 37764697, 2023). "Despite these findings, our studies also confirm that glucagon is an attractive metabolic disease therapeutic as it improves glycemia and hepatic steatosis in the context of dietary protein supplementation, an intervention that helps to prevent lean mass loss." (PMID 36384093, 2022). "The expression of this gene can be regulated by insulin, glucocorticoids, glucagon, cAMP, and diet and it has multiple relationships with several metabolic diseases." (PMID 32957918, 2020).
metabolic disease (continued). "The concept of glucagon resistance must be further investigated before conclusions about its relevance in metabolic diseases can be reached." (PMID 31284506, 2019). "The elevated glucagon levels seen in metabolic diseases could represent an adaptive mechanism to sustain energy balance and β-cell activity." (PMID 41149695, 2025). "This review aims to provide a comprehensive overview of the pathophysiological role of glucagon in metabolic diseases, synthesizing recent findings that support novel hypotheses for the management and prevention of these conditions." (PMID 41149695, 2025). "Our findings confirm that dual agonism promotes hepatic, metabolic and body weight loss benefits associated with the combined action of glucagon and GLP-1, which could directly underpin the therapeutic effect as a potential treatment for metabolic diseases." (PMID 38066113, 2023). "We found that the BCD could deliver an accurate amount of a drug, such as exenatide, insulin, or glucagon, which was as effective as conventional injections in an animal model of metabolic disease." (PMID 36684080, 2023). "However, the complex interplay between glucagon and fatty acids requires further elucidation to understand its implications in metabolic diseases." (PMID 37764697, 2023). "The LACA may provide better insight into metabolic diseases, and the dynamics of glucagon and amino acids during standardized glucose challenge tests may hold a predictive or diagnostic value." (PMID 36686477, 2022). "Dapagliflozin directly causing glucagon secretion from the pancreas may explain why the incident rate for DKA and total metabolic disorders were the highest, 16.09 and 25.54, respectively." (PMID 34586753, 2021). "In addition, glutamic acid may also be triggered by glucagon release from alpha‐pancreatic cells, aggravating metabolic diseases." (PMID 37622725, 2023). "Although we found subtle changes to some key factors, including leptin and glucagon levels in the blood, the study did not reveal strong evidence for heightened risk of metabolic disease or a propensity for weight gain, or any strong new candidates to serve as biomarkers." (PMID 29321614, 2018). "Gut-pancreatic peptides such as glucose-dependent insulinotropic polypeptide (GIP), glucagon, amylin, and peptide YY (PYY) are of particular interest due to their distinct pharmacological benefits and therapeutic promise in metabolic disorders." (PMID 42307179, 2026). "In the context of metabolic diseases such as NAFLD and SMA, liver dysfunction, including impaired lipid metabolism, may disrupt this axis, leading to abnormal glucagon secretion." (PMID 39976226, 2025). "Glucagon and GLP-1 receptor dual agonists and GLP-1, GIP, and glucagon receptor triple agonists have been developed, and we will be able to use them for the treatment of metabolic diseases including type 2 diabetes, in future." (PMID 40607157, 2024). "Altogether, our results reveal that gut galanin modulates glucagon release to augment energy wasting in SD mice and provide novel pharmaceutical opportunities for the treatment of metabolic disorders in SD patients." (PMID 37221172, 2023). "Most DEGs were related to substances related to metabolic diseases, such as thyroid hormone synthesis, the AMPK signaling pathway, the glucagon signaling pathway, insulin secretion, fatty acid biosynthesis, cortisol synthesis and secretion and vasopressin-regulated water reabsorption." (PMID 35954098, 2022). "A hypothesis posits that glucagon resistance, a molecular phenomenon impacting glucagon’s physiological effects on glucose, amino acid (AA), and lipid metabolism, might contribute to the development of T2DM and metabolic diseases." (PMID 37764697, 2023). "Indeed, the cross reaction of glucagon at the GLP-1R has proven to be vital for pancreas function and dual (or triple) agonists of the GCGR and GLP-1R (and GIP receptor) are currently being studied for the treatment of metabolic disorders." (PMID 36009454, 2022).
metabolic disease (continued). "There is very solid evidence that glucagon is an important hormone in human and mammalian metabolism, but its precise physiological role in glucose and lipid metabolism and in metabolic disease has been difficult to establish, not least because of these difficulties." (PMID 31671667, 2019). "The described approach will allow to study insulin secretion also in other metabolic disorders possibly affecting C-peptide kinetics (e.g., renal diseases) or to study secretion of other hormones for which a population model of the kinetics is not yet available (e.g., glucagon)." (PMID 33790855, 2021).
tumor (117 papers, 2005 to 2026). "The subversive loop is influenced by glucagon levels in the tumour and organ microenvironment (TOME), as well as the mutational profile and expression levels of the GCGR and GLP-1R." (PMID 40649254, 2025). "Our study found that GCGR expression was inversely associated with tumour grade, suggesting possible differences in glucagon signalling between early-stage and more advanced tumours." (PMID 40649254, 2025). "In conclusion, comprehensive bioinformatics analysis showed that GCG was significantly downregulated in COADREAD tumor samples and associated with worse prognostic outcomes." (PMID 35340411, 2022). "Overall, these findings point to the complex role of GCG in regulating the tumor immune microenvironment, whereby a hyperinflammatory environment appears to be associated with upregulation of GCG in COADREAD." (PMID 35340411, 2022). "Several tumor progression-related pathways and tumor immune-modulatory cells were linked to GCG expression in COADREAD." (PMID 35340411, 2022). "Since fly Akh and mammalian glucagon are conserved catabolic hormones, we wonder whether neural-associated glucagon release also participates in tumor-induced host wasting in mammals." (PMID 39924534, 2025). "Previous results have indicated that excessive glucagon response also potently results in weight decline, lipid loss, and muscle atrophy in mice, we next investigate whether glucagon is essential for tumor-induced systemic wasting." (PMID 39924534, 2025). "These tumors may secrete excessive quantities of hormone such as gastrin, insulin, vasoactive intestinal polypeptide (VIP), glucagon, or somatostatin and may be associated with distinct clinical syndromes, with approximately one third of these neoplasms becoming clinically apparent." (PMID 31263451, 2019). "Processes related to glucagon metabolism (e.g. “response to glucagon”) and ATP synthesis are more active in the invasive tumor region, while processes related to anoikis (e.g. “regulation of anoikis”) are repressed in the invasive tumor region." (PMID 41160880, 2026). "Hyperglucagonemia appears to play a central role, as normalizing glucagon concentrations through tumor resection typically leads to rapid improvement in the skin lesions." (PMID 41403981, 2025). "The diagnosis of glucagonoma is often made in the context of glucagonoma syndrome, which is characterized by the autonomous secretion of glucagon by the tumor." (PMID 41403981, 2025). "Clinically, the high prevalence of GCGR expression in pNET tissues and its inverse correlation with tumour grade, alongside the reduced GLP-1R expression, point to disrupted insulin–glucagon signalling in tumour progression." (PMID 40649254, 2025). "Glucagonoma, a rare tumor that produces high levels of glucagon, was excluded in advance in this study." (PMID 39924534, 2025). "Given glucagon’s role as a metabolic regulator, it is essential to investigate how systemic metabolism and dietary factors influence tumour progression." (PMID 40649254, 2025). "Instead of isolated proteins, we identified a downregulated network of EEC markers (CHGA, GCG, PYY, NEUROD1) associated with tumor processes, reduced survival, and poor chemotherapy responses." (PMID 41303610, 2025). "Similar to GLP1R, GCG expression was significantly decreased in tumor tissues compared to normal tissues (p = 2.47e-03), with a more pronounced reduction in metastatic tissues (p = 5.57e-09)." (PMID 39777709, 2025). "In around 87% of cases, the glucagon-producing tumor is found in the body or tail of the pancreas, while the rest are situated predominantly in the head of the pancreas." (PMID 41567922, 2025). "Complete tumor removal results in the rapid cessation of glucagon hypersecretion, leading to the resolution of diarrhea, an improvement in mucocutaneous symptoms, such as necrolytic migratory erythema, and the reversal of catabolic processes." (PMID 40647278, 2025).